ATG3 (autophagy related 3)
Description:
E2 conjugating enzyme that catalyzes the covalent conjugation of the C-terminal Gly of ATG8-like proteins (GABARAP, GABARAPL1, GABARAPL2 or MAP1LC3A) to the amino group of phosphatidylethanolamine (PE)-containing lipids in the membrane resulting in membrane-bound ATG8-like proteins which is one of the key steps in the development of autophagic isolation membranes during autophagosome formation. Cycles back and forth between binding to ATG7 for loading with the ATG8-like proteins and binding to E3 enzyme, composed of ATG12, ATG5 and ATG16L1 to promote ATG8-like proteins lipidation. Also plays a role as a membrane curvature sensor that facilitates LC3/GABARAP lipidation by sensing local membrane stress associated with lipid-packing defects as occurs with high molar proportions of conical lipids or strident membrane curvature (By similarity). Interacts with negatively-charged membranes promoting membrane tethering and enhancing LC3/GABARAP lipidation. Also acts as an autocatalytic E2-like enzyme by catalyzing the conjugation of ATG12 to itself in an ATG7-dependent manner, this complex thus formed, plays a role in mitochondrial homeostasis but not in autophagy (By similarity). ATG12-ATG3 conjugation promotes late endosome to lysosome trafficking and basal autophagosome maturation via its interaction with PDCD6IP (By similarity). ATG12-ATG3 conjugate is also formed upon viccina virus infection, leading to the disruption the cellular autophagy which is not necessary for vaccinia survival and proliferation (By similarity). Promotes primary ciliogenesis by removing OFD1 from centriolar satellites via the autophagic pathway (By similarity).
Synonyms: APG3-like; hApg3; APG3; APG3L; PC3-96; FLJ22125; MGC15201; DKFZp564M1178
Tractability: Antibody: the Human Protein Atlas places it where antibodies can reach. PROTAC: UniProt records ubiquitination sites on it; ubiquitination databases record sites on it; its protein half-life has been measured.
Gene: Protein-coding gene on chromosome 3 (112,532,510 to 112,562,046, reverse strand). Ensembl gene ENSG00000144848.
Subcellular location: Cytoplasm
Subcellular location (Human Protein Atlas): Cytosol; Plasma membrane
Pathways (Reactome):
Autophagy: Macroautophagy
Gene Ontology:
Molecular function: Atg8-family conjugating enzyme activity; enzyme binding; protein binding; ubiquitin-like protein transferase activity; Atg12 transferase activity; Atg8-family ligase activity
Biological process: autophagosome assembly; protein ubiquitination; autophagy of mitochondrion; glycophagy; mitochondrial fragmentation involved in apoptotic process; nucleophagy; protein targeting to membrane; regulation of cilium assembly; autophagy
Cellular component: Atg12-Atg5-Atg16 complex; cytoplasm; cytosol; plasma membrane; phagophore assembly site
Genetic constraint (gnomAD): Loss-of-function variants: 13 observed, 23.31 expected, observed/expected ratio (o/e) 0.56, 90% interval 0.36 to 0.89. The upper end of that interval is the gene's LOEUF score, 0.89, which puts it in group 3 of 6, group 1 being the genes least tolerant of losing a copy. Missense variants: 204 observed, 259.27 expected, observed/expected ratio (o/e) 0.79, 90% interval 0.7 to 0.88. Synonymous variants: 89 observed, 90.46 expected, observed/expected ratio (o/e) 0.98, 90% interval 0.83 to 1.17.
Homologues: Orthologues: chimpanzee ATG3 (100% identical), macaque ATG3 (99% identical), rabbit ATG3 (98% identical), guinea pig ATG3 (98% identical), dog ATG3 (98% identical), mouse Atg3 (97% identical), pig ATG3 (90% identical), rat Atg3 (89% identical), tropical clawed frog atg3 (85% identical), zebrafish atg3 (84% identical), Drosophila melanogaster Atg3 (65% identical), Caenorhabditis elegans atg-3 (54% identical).
Diseases named in the same sentence as ATG3 in open-access papers:
ATG3 is named in the same sentence as 85 diseases in open-access papers, as found by Europe PMC text mining. Sharing a sentence is not in itself a finding about the gene and the disease. The quoted sentences say what the papers report.
breast cancer (13 papers, 2015 to 2025). A primary or metastatic malignant neoplasm involving the breast. "LncRNA GAS5 regulates autophagy in breast cancer through the GAS5-miR-23a-ATG3 axis, and GAS5 expression is down-regulated in breast cancer." (PMID 35813295, 2022). "To further validate autophagic induction in breast cancer cells, we measured the protein levels of Beclin-1, Atg3, and the conversion of LC3-I to LC3-II which are the hallmarks of autophagy induction." (PMID 33013353, 2020). "ATG3 was observed to be upregulated in various kinds of tumor tissues, which played an oncogenic role in colon cancer and breast cancer." (PMID 33160404, 2020). "The KM plotter analysis points thatsignificant upregulation of ATG3, ATG5, PIK3R4, and ATG8B to be linked with poor prognosis of Tamoxifen treated breast cancer patients." (PMID 34621117, 2020). "Furthermore, higher ATG3, ATG5, and ATG12 expression levels are associated with a lower overall survival rate in breast cancer patients, indicating a predictive value of these genes." (PMID 40426890, 2025). "Its high expression resulted in poor prognosis of breast cancer patients treated with Tamoxifen as indicated by p-value=0.033 and HR =1.39 (1.39-1.88).ATG3 plays an important role in the process of autophagy by promoting the conversion between LC3I and LC3II during autophagy execution." (PMID 34621117, 2020). "was found to induce autophagic cell death in HER2-overexpressing BT-474 breast cancer cells leading to a vacuole formation and increasing levels for autophagy markers (e.g., LC3A/B, ATG3, ATG7, and ATG16L) in human breast cancer cells." (PMID 27537898, 2016). "Finally, we investigated the autophagic state of these same human breast cancer tissues by IHC staining for the autophagy mediators p62/SQSTM1, LC3, and Atg3, whose expression was compared with that of Pfkfb3." (PMID 31413316, 2019). "Interestingly, araguspongine C-induced autophagic cell death in HER2-overexpressing BT-474 breast cancer cells was characterized by vacuole formation and upregulation of autophagy markers including LC3A/B, Atg3, Atg7, and Atg16L." (PMID 25580621, 2015).
hepatocellular carcinoma (13 papers, 2018 to 2025). A malignant tumor that arises from hepatocytes. "For instance, NEAT1 upregulates ATG3 to enhance autophagy, thereby increasing resistance to sorafenib in hepatocellular carcinoma cells." (PMID 39715205, 2024). "NEAT1 promotes autophagy and fortifies cell resistance to sorafenib through sponging miR-204 and modulating ATG3 in hepatocellular carcinoma." (PMID 31868202, 2020). "LncRNA HOTAIR has been demonstrated to be overexpressed in hepatocellular carcinoma (HCC), also promoting autophagy in these cells by upregulating ATG3 and ATG7 at mRNA and protein levels." (PMID 35309939, 2022). "LncRNA nuclear-enriched abundant transcript 1 (NEAT1) activates autophagy via regulating ATG3 or Beclin1 expression and inhibits chemotherapeutic efficacy in hepatocellular carcinoma (HCC) and colorectal cancer." (PMID 33239065, 2020). "Meanwhile, HOTAIR has also been shown to enhance cell autophagy through up-regulation of ATG3 and ATG7 in hepatocellular carcinoma." (PMID 32396526, 2020). "Moreover, autophagy triggered by starvation initiates EMT and invasion in hepatocellular carcinoma (HCC) cells through TGF-β/Smad3 signaling, and inhibition of autophagy by depleting Atg3 or Atg7 abolishes this effect." (PMID 38741166, 2024). "In addition, some studies found that lncRNAs and Phosphoinositides (PIs) could activates autophagy by upregulating ATG3 and ATG7 in hepatocellular carcinoma." (PMID 29895332, 2018). "Moreover, NEAT1 could contribute to cell proliferation, apoptosis, and invasion in lung cancer via the miR-1224/Kruppel like factor 3 (KLF3) axis, and promoted autophagy by regulating miR-204/autophagy related 3 (ATG3) and enhanced cell resistance to sorafenib in hepatocellular carcinoma." (PMID 33738254, 2021).
lung cancer (8 papers, 2012 to 2023). A malignant neoplasm involving the lung. "It has been proved that KCNQ1OT1 can promote cell proliferation and autophagy and inhibit cell apoptosis by regulating mir‐204‐5p/ATG3 axis, which provides a promising target for non‐small cell lung cancer (NSCLC) treatment." (PMID 34850551, 2022). "The present study indicated that cisplatin at the maximum response concentration mediated autophagy through the induction of OH·, which subsequently activated Atg3 and Atg7 and led to apoptosis resistance in human lung cancer H460 cells." (PMID 34321115, 2021). "In conformity with pro-survival autophagy modulated by OH·, resistance to cisplatin-induced cell death, as well as the overexpression of Atg3 and Atg7 in human lung cancer cells cultured with cisplatin was repressed by pre-incubation the cells with deferoxamine." (PMID 34321115, 2021). "After ESI treatment, autophagy markers such as ATG3, LC3-II and Beclin1 in lung cancer cells increased significantly, and therapeutic effects were produced through various channels." (PMID 37666811, 2023). "Icotinib increased ATG3, ATG5, and ATG7 expression, but without affecting Beclin-1, VPS34 and ATBG14 levels in icotinib-resistant lung cancer cells." (PMID 35690866, 2022).
viral infection (7 papers, 2017 to 2025). "Our investigation into whether atg-3 mutation mediates viral infection pre- or post-entry using the replicon system revealed similar levels of RNA1 in WT and rde-1-mutant C. elegans after heatshock." (PMID 41252446, 2025). "ATG3 was included among the common transcripts downregulated in response to viral infection and may be implicated in ubiquitin-like conjugation systems that prolong the autophagosomal membrane phase." (PMID 36292879, 2022). "In contrast, we observed numerous prominent clusters of viral particles in the atg-3 mutants, consistent with increased viral infection." (PMID 39868230, 2025). "As RDE-1 limits viral infection at a post-entry step, the similarity in induction of GFP expression in the replicon system suggest that ATG-3 also limits viral infection at a post-entry step." (PMID 41252446, 2025). "We next confirmed that atg-3-mutant C. elegans are hypersusceptible to Orsay virus infection compared to WT animals at an earlier timepoint of 48 hpi as well." (PMID 41252446, 2025). "We found that ATG-3 limits viral infection at a post-entry step independently from its role in maintaining autophagic flux." (PMID 41252446, 2025). "We assumed that in A. mellifera, ATG3 was downregulated in response to viral infection to avoid the host immune response and autophagy." (PMID 36292879, 2022). "In contrast, autophagy-related protein 3 (ATG3) (MSTRG.1676.15) was included among the transcripts downregulated in response to viral infection while urea transporter transcript (MSTRG.12160.40) was downregulated in response to bacterial infection." (PMID 36292879, 2022). "To further research what roles autophagy or Atg genes played in the process of BmNPV infection, we choose Atg genes with the greatest fold change (Atg3, 4, 5, 7, 9, and 12) to find their relationships with virus infection." (PMID 29301200, 2017). "In addition, we found that ATG-3 likely limits viral infection at a post-entry step, similar to RDE-1." (PMID 41252446, 2025). "In addition, functions of ATG3 are emerging in many contexts, including the maintenance of mitochondrial homeostasis, regulation of tumor progression, and clearance of viral infection." (PMID 34235149, 2021). "Additionally, atg-3 limits viral infection at a post-entry step, similar to rde-1 mutants." (PMID 39868230, 2025). "Additionally, ATG-3 limits viral infection at a post-entry step, similar to RDE-1." (PMID 41252446, 2025). "In addition, we found that ATG-3 limits viral infection at a post-entry step, similar to RDE1." (PMID 39868230, 2025). "Thus, ATG-3 limits viral infection at a post-entry step, similar to RDE-1." (PMID 39868230, 2025). "As rde-1 mechanistically modulates viral infection through a defect in RNAi, which acts post-viral entry, the similarity between GFP induction in replicon rde-1 and atg-3 mutants compared to WT animals suggests that atg-3 also acts post-viral entry." (PMID 41252446, 2025). "However, key autophagy genes including ATG1, ATG3, ATG9, ATG12, and ATG16L1 were significantly upregulated in horses after viral infection." (PMID 39287214, 2024).
ovarian carcinoma (6 papers, 2017 to 2023). A malignant neoplasm originating from the surface ovarian epithelium. "The results of the data analysis indicated that the contents of ATF4, GPX4, GSS, KEAP1, and ATG3 in the peripheral blood exosomes of patients with ovarian cancer were significantly higher than those of the healthy controls." (PMID 37215446, 2023). "Human maternally expressed gene 3 (lncRNA MEG3) promotes autophagy by protecting autophagy-related 3 (ATG3) from degradation in ovarian cancer." (PMID 32429086, 2020). "For example, Nrf2 induction by cisplatin is linked to the increased expression of autophagy-related genes, including Atg3, Beclin1 and Atg12, which contributes to the resistance against cisplatin treatment in ovarian cancer cells." (PMID 28341848, 2017). "Finally, analysis using a peripheral blood exosome database indicated that the contents of key factors (e.g., ATF4, GPX4, and ATG3) in peripheral blood exosomes from patients with ovarian cancer, were significantly higher than those of the healthy controls." (PMID 37215446, 2023). "In addition, we performed exosome database screening and found that the levels of ATF4, GPX4, GSS, KEAP1, and ATG3 in the peripheral blood exosomes of patients with ovarian cancer were significantly higher than those from the healthy controls." (PMID 37215446, 2023). "Finally, we explored whether factors such as ATF4, GPX4, GSS, KEAP1, NFE2 like BZIP transcription factor 2 (NEF2L2), SLC7A11, SQSTM1, ATG3, ATG4D, and ATG5 have potential as non-invasive diagnostic markers for ovarian cancer." (PMID 37215446, 2023). "A study pointed out that curcumin could induce the formation of autophagic vesicle by suppressing AKT/mTOR/p70S6K pathway in ovarian cancer A2780 cells, and enhancing the expression of microtubule-associated protein light chain 3B I/II (LC3B-I/II), autophagy-related 3 (Atg3) and Beclin1." (PMID 36009200, 2022). "Kaplan-Meier plot analysis indicated that the expression levels of GSS, KEAP1, ATG3, and ATG4D correlated significantly and negatively with the survival of patients with ovarian cancer." (PMID 37215446, 2023). "The results of cDNA expression profile analysis indicated that six genes, including GPX4, GSS, KEAP1, SQSTM1, SLC7A11, ATG3, and ATG5, were highly expressed in tumor tissues from patients with ovarian cancer." (PMID 37215446, 2023). "The results of multiple gene correlation analyses indicated that there was a significant linear relationship (positive correlation) between the expression of ATF4 in ovarian cancer tissue and the expression levels of GPX4, GSS, KEAP1, NFE2L2, SLC7A11, ATG3, ATG4D, and ATG5." (PMID 37215446, 2023). "A group from China Medical University revealed that MEG3 may be a potential biomarker for epithelial ovarian cancer (EOC) and acts as a tumor suppressor in EOC by modulating autophagy-related 3 (ATG3) activity and triggering autophagy." (PMID 36544907, 2022).
prostate carcinoma (6 papers, 2017 to 2024). A carcinoma that arises from epithelial cells of the prostate gland. "Because our data showed that TNFAIP8 modulated autophagy markers, we hypothesized that TNFAIP8 may interact with ATG3 or other autophagy-related proteins in prostate cancer cells." (PMID 29928491, 2018). "In prostate cancer cells, TNFAIP8 can interact with ATG3 and subsequently create cellular autophagy events that promote cell survival and drug resistance, thereby indicating that ATG3 may play different roles in different cancers." (PMID 34235149, 2021).
colon cancer (5 papers, 2020 to 2025). "For example, ATG3 knockdown remarkably suppressed the proliferation and invasion of colon cancer cells." (PMID 34235149, 2021). "As a result, ATG3 could promote proliferation and invasion in colon cancer, whereas the downregulation of ATG3 could suppress the progression of colon cancer." (PMID 34235149, 2021). "Upregulation of miR-431-5p prohibits cell proliferation and invasion via ATG3 in colon cancer." (PMID 33023644, 2020). "However, another study showed that in colon cancer tissues, the expression of ATG3 was upregulated." (PMID 34235149, 2021). "Moreover, miR-431-5p is reported to decrease the expression of ATG3 in colon cancer." (PMID 33160404, 2020).
liver cancer (5 papers, 2019 to 2025). An epithelial or non-epithelial malignant neoplasm that arises from the liver. "For instance, betaine enhances autophagy and inhibits liver cancer stem cell traits by increasing m6A modification on autophagy-related gene 3 (ATG3) mRNA and facilitating YTHDF1 binding, which in turn stabilizes ATG3 transcripts." (PMID 41446042, 2025). "SMAD2 and SMAD3 correlated with autophagy-related scores (based on ATG12, ATG7, ATG3, ATG5, ATG4B, PIK3C3, PRKAA2, and GABARAPL1) in liver cancer." (PMID 37790613, 2023). "In liver cancer, lncRNA NEAT1 increases autophagy by controlling miR-204/ATG3 and increases cell resilience to sorafenib." (PMID 37790613, 2023). "Overexpression of HOTAIR can elevate the expression of autophagy-related 3 (ATG3) and ATG7 expression to trigger autophagy and promote HCC cell proliferation, and induce EMT of liver cancer stem cells (LCSCs) by downregulating E-cadherin." (PMID 31480503, 2019).
non-small cell lung carcinoma (5 papers, 2021 to 2024). A group of at least three distinct histological types of lung cancer, including non-small cell squamous cell carcinoma, adenocarcinoma, and large cell carcinoma. "For instance, overexpressed miR-1-3p restrains autophagy via targeting ATG3 in non-small cell lung cancer." (PMID 34124097, 2021). "In non-small cell lung cancer (NSCLC) patients, the expression level of miR-16 was significantly downregulated, whereas that of ATG3 was upregulated, with the 3’-UTR of ATG3 as the direct target of miR-16." (PMID 34235149, 2021).
gastric cancer (4 papers, 2017 to 2023). A primary or metastatic malignant neoplasm involving the stomach. "In gastric cancer, low expression of ATG10 and ATG3 were associated with lymph node metastasis and advanced TNM stage; both ATG10 and ATG3 were found to be favorable independent prognostic factors for overall survival." (PMID 28696368, 2017). "Moreover, correlation analysis showed that TOB1 was positively correlated with the expression of ATG3 and ATG7 in gastric cancer but not in normal gastric tissue." (PMID 35186488, 2022). "The expression level of TOB1 was positively correlated with the expression levels of ATG3 (R = 0.32, ***P = 2 × e−11) and ATG7 (R = 0.23, ***P = 1.7 × e−06) in gastric cancer tissues but not in normal gastric tissue (ATG3, R = 0.027, P = 0.7; ATG7, R = 0.033, P = 0.64)." (PMID 35186488, 2022).